DPP4 (dipeptidyl peptidase 4)
Diseases named in the same sentence as DPP4 in open-access papers (continued):
Sharing a sentence is not in itself a finding about the gene and the disease.
diabetes (continued). "Modulation of the incretin system can be used to treat diabetes, with two approved therapies currently available, dipeptidyl peptidase 4 (DPP-4) inhibitors and GLP-1 receptor agonists." (PMID 29623219, 2018). "Inhibition of the DPP-4 enzyme played an important role in controlling the phenotypes of severe diseases, such as diabetes, obesity, and cancer, by preventing the inhibition of incretin hormones." (PMID 29882783, 2018). "Recently, novel serine protease dipeptidyl peptidase-4 (DPP-4) inhibitors played a role in the management of diabetes, obesity, and cancer." (PMID 29882783, 2018). "Dipeptidyl peptidase-4 (DPP-4) inhibitors are therapeutic drugs used in patients with diabetes because they activate incretin hormones such as glucagon-like peptide-1." (PMID 30151063, 2018). "Based on the results of this work, chrysin as a DPP-4 inhibitor can be used alone or in combination with current chemotherapies to improve treatment for diabetes, obesity, and cancer." (PMID 29882783, 2018). "In rats either fed high-fat diets or treated with streptozotocin (STZ) to induce diabetes, DPP-4 was overexpressed in renal tubular cells." (PMID 29491123, 2018). "By understanding the enzyme structure, its motions and the regions of its binding sites, it will be possible to contribute to the design of new DPP-4 inhibitors as drug candidates to treat diabetes." (PMID 29473857, 2018). "Here, we showed that both the GLP‐1 analog exendin‐4 and the DPP‐4 inhibitor saxagliptin improved the diabetes phenotype, mitigated heart damage, hyperglycemia, insulin resistance, myocardial remodeling, and cardiac dysfunction." (PMID 29659121, 2018). "Trelagliptin (TRG) is a dipeptidyl peptidase-4 (DPP-4) inhibitor for treating type 2 diabetes mellitus as a once-weekly monotherapy." (PMID 29629213, 2018). "Dipeptidyl-peptidase 4 (DPP-4) inhibitors (gliptins) are oral antidiabetic drugs used to treat type 2 diabetes mellitus (T2D)." (PMID 29776406, 2018). "This real-world analysis suggests that DM2 patients initiating third-line therapy with NPH have poorer control of diabetes when compared to DPP-4 inhibitor initiators." (PMID 29713649, 2018). "On discharge, 27% of the diabetes group were taking metformin, 31% were taking a sulphonylurea, 7% were on a DPP-4 inhibitor and 36% were prescribed insulin." (PMID 30202020, 2018). "Dipeptidyl peptidase-4 (Dpp4) is a cell surface serine protease known as an important target of diabetes treatment, as well as a secreted factor released from adipogenic cells which is negatively correlated with bone mass." (PMID 29955232, 2018). "Other studies have also found a correlation between increased DPP-4 activity and diabetic and non-diabetic kidney disease." (PMID 29491123, 2018). "The cardiovascular safety and efficacy of linagliptin, a dipeptidyl peptidase-4 inhibitor, in patients with type 2 diabetes mellitus (T2DM) after acute coronary syndrome (ACS) or acute ischemic stroke (AIS) are unclear." (PMID 29301579, 2018). "Evidence supporting the use of DPP-4 inhibitors in post-transplant diabetes comes mainly from kidney recipients." (PMID 29411291, 2018). "The patient was diagnosed with diabetes mellitus based on the fasting plasma glucose levels and haemoglobin A1c (HbA1c) levels during regular visits and was started on a dipeptidyl peptidase-4 (DPP-4) inhibitor and Pioglitazone in 2012." (PMID 30526529, 2018). "When she entered the keyword “dipeptidyl peptidase 4,” the diabetes drug sitagliptin that targets the dipeptidyl peptidase 4 protein appeared in the graph as a connected concept, with accompanying information on relevant drug trials, targets, and interactions." (PMID 30271306, 2018). "In contrast to the upregulation of DPP-4 expression observed in renal tissues injured by diabetes, obesity, and free fatty acid-bound albumin, the present study showed that DPP-4 expression was downregulated in rat renal tissues injected with MCT." (PMID 29607314, 2018).
diabetes (continued). "In England there is extensive geographical variation in the prescribing of diabetes drugs after metformin, and increasing use of higher‐cost DPP‐4 inhibitors and SGLT‐2 inhibitors compared with low‐cost sulphonylureas." (PMID 29732725, 2018). "Signature genes included previously reported beta-specific genes like NKX6-1, DLK1, and ADCYAP1 (right) and alpha cell–specific genes like IRX2, LOXL4, and DPP4, a cell surface receptor and diabetes drug target." (PMID 27864352, 2017). "All countries and cantons have basic medications for treatment of diabetes, while few also provide newer antidiabetic agents, such as DPP4 inhibitors and SGLT2 inhibitors (which are additionally charged)." (PMID 29167787, 2017). "We also detected the DPP-4 activity in serum and found that saxagliptin dramatically decreased the diabetes-enhanced DPP-4 activity in HFD/STZ-induced diabetic rats." (PMID 29230196, 2017). "This is the first pharmacogenomics study on DPP-4 inhibitor treatment for diabetes in a Taiwanese population." (PMID 28160554, 2017). "Trelagliptin (TRL) is a new antidiabetic drug that administered as a monotherapy for the treatment of diabetes mellitus (type II) and classified as one of dipeptidyl peptidase-4 (DPP-4) inhibitors." (PMID 29222475, 2017). "Omarigliptin is a once-weekly (q.w.)oral DPP-4 inhibitor that is approved for the treatment of patients with type 2 diabetes mellitus (T2DM) in Japan." (PMID 28893244, 2017). "The differences between Poland and other countries were observed in the adoption of new antidiabetic drugs, e.g. in 2012 the share of DPP-4 inhibitors in the diabetes medication market amounted to approx. 10% in US and UK, and only 0.003% in Poland." (PMID 28582404, 2017). "Dipeptidyl peptidase IV (DPP-4) inhibitors are one of the newest therapeutic agents against type 2 diabetes mellitus." (PMID 29318154, 2017). "Preclinical data have shown that vildagliptin, a DPP-4 inhibitor, can prevent peripheral nerve degeneration in a diabetes-induced animal model." (PMID 29340105, 2017). "The MSN nano-vehicle has several advantages in delivering natural DPP4 inhibitor to act against diabetes with slow release of HCD and reduced levels of TG, GOT, and GTP without adverse effects." (PMID 28498352, 2017). "Since DPP4 is a therapeutic target for diabetes, most studies on DPP4 are carried out in diabetic patients." (PMID 28587613, 2017). "GLP-1 analogues and DPP-4 inhibitors has been used for the treatment of diabetes mellitus by increasing GLP-1 concentrations in the blood." (PMID 29100378, 2017). "GLP-1R is initially found expressing in pancreatic islets cells and activated GLP-1R induces insulin synthesis and release; thus, GLP-1R agonists or dipeptidyl peptidase 4 (DPP-4) inhibitors have been used in the treatment of type 2 diabetes mellitus (T2DM)." (PMID 28846606, 2017). "At present, DPP-4 inhibitor is very often used for the treatment of type 2 diabetes mellitus and exerts beneficial effects including glucose-lowering effect in many subjects with type 2 diabetes." (PMID 28626771, 2017). "These glucose level-dependent mechanisms of incretins suggest that DPP-4 inhibitors can improve glycemic control and reduce glucose fluctuations in patients with type 2 diabetes mellitus compared with other insulin secretagogues." (PMID 28725273, 2017). "Omarigliptin is an oral dipeptidyl peptidase-4 (DPP-4) inhibitor for the treatment of type 2 diabetes mellitus (T2DM) with a half-life that allows once-weekly dosing." (PMID 28893244, 2017). "Dipeptidyl peptidase 4 inhibitors are used worldwide in the management of diabetes, but their role in the prevention or treatment of cardiovascular disorders has yet to be defined." (PMID 28771625, 2017). "Incretin-based therapies by using the oral form of dipeptidyl peptidase-4 (DPP-4) inhibitors have become a mainstay in the treatment of type 2 diabetes mellitus." (PMID 29228568, 2017).
diabetes (continued). "Dipeptidyl peptidase-4 inhibitors (DPP-4 inhibitors) are classified as a new oral anti-diabetic medication and are widely used for management of type 2 diabetes mellitus." (PMID 29213240, 2017). "Dipeptidyl peptidase-4 (DPP-4) inhibitors are widely used antihyperglycemic agents for the treatment of type 2 diabetes mellitus." (PMID 29317794, 2017). "Since then, an increasing number of cardiovascular outcome trials have been completed in diabetes patients with high cardiovascular risk for members of the SGLT-2 and DPP4 inhibitors and GLP-1 receptor agonist classes." (PMID 29020969, 2017). "It is well known that DPP-4 promotes the pathology of diabetes via catalytic degradation of glucagon-like peptide-1 (GLP-1) and gastric inhibitory peptide (GIP), which induce postprandial secretion of insulin by pancreatic β-cells." (PMID 28771625, 2017). "In a murine experimental diabetes model, DPP-4 inhibition was shown to attenuate cardiac dysfunction and adverse remodeling in the post-MI setting." (PMID 28697774, 2017). "Dipeptidyl peptidase-4 (DPP-4) inhibitors are oral agents used for the pharmacological treatment of adults with type 2 diabetes mellitus." (PMID 29047372, 2017). "Prolonging the half-life of GLP-1 in order to extend its insulinotropic effect is the principle rationale for use of DPP-4 inhibitors for treatment of hyperglycemia in diabetes." (PMID 28476142, 2017). "Patients in the DPP-4 inhibitors group had more diabetes-related complications and less couse of other blood glucose lowering drugs than glimepiride, excluding metformin and sulfonylureas (except glimepiride)." (PMID 28640111, 2017). "Gut peptides such as GLP-2 decrease turnover in response to feeding, and there has been interest in the possible bone effects of GLP-1 analogues and dipeptidyl peptidase 4 (DPP-4) inhibitors in diabetes treatment." (PMID 28280846, 2017). "Elevated levels of DPP-4, TGF-β/smad signaling and downregulation of anti-fibrotic miRs in the fibrotic strain have been associated with increased EndMT in diabetes." (PMID 27425816, 2016). "saxagliptin also belonging to the same category of DPP4 inhibitors, results from Januvia Diabetes Economic model can be extrapolated to demonstrate potential cost effectiveness of saxagliptin in a similar way." (PMID 27388897, 2016). "Medication for type 2 diabetes mellitus included biguanides (17.9%), DPP-4 inhibitors (46.2%) and sulfonylureas (5.1%)." (PMID 27124282, 2016). "We searched published articles and other documents related to phase III placebo-control trials of DPP-4 inhibitors in Type 2 diabetes mellitus (T2DM)." (PMID 27600598, 2016). "Recently, new orally administered dipeptidyl peptidase 4 (DPP-4) inhibitors have become available for the treatment of diabetes." (PMID 27809848, 2016). "Given the high incidence of coronary artery disease in patients with diabetes mellitus, many factors require clarification before DPP-4 inhibitors can be considered as an adjunctive treatment after MI." (PMID 26811539, 2016). "Vildagliptin is a potent, orally active inhibitor of dipeptidyl peptidase-4 (DPP-4) for the treatment of type 2 diabetes mellitus." (PMID 27759084, 2016). "In the clinical trial setting, trelagliptin showed sustained inhibition of DPP-4 activity until 7 days after dosing in the phase 2 dose-ranging study in patients with type 2 diabetes mellitus (T2DM)." (PMID 27328054, 2016). "In EC, DPP-4 expression is increased in models of diabetes and in VSMC, DPP-4 expression is preferentially increased in conditions of vascular remodeling." (PMID 27391040, 2016). "Relatively few studies have examined the effects of DPP-4 inhibitors on BP in patients with diabetes." (PMID 27036865, 2016). "Diabetes led to a 26% increase in plasma DPP4 activity ([N] 1.6 ± 0.5 x 105 AU vs [D] 2.0 ± 0.7 x 105 AU; P < 0.05), whereas linagliptin reduced DPP4 activity by 77% (0.5 ± 0.1 x 105 AU vs [D] P < 0.001)." (PMID 27942008, 2016).
diabetes (continued). "According to the German Diabetes Association (DDG), the primary advantage of DPP-4 inhibitors in comparison to the older sulfonylureas is the decreased risk of hypoglycaemia." (PMID 27760528, 2016). "The results of the current study demonstrate the novel therapeutic potential of DPP-4 inhibitors for the extension of lifespan in diabetes patients." (PMID 26937254, 2016). "Dipeptidyl peptidase-4 (DPP-4) inhibitors are incretin-based therapies for type 2 diabetes mellitus." (PMID 26886601, 2016). "A few recent clinical studies have demonstrated increased blood DPP4 activity in subclinical atherosclerosis (diabetes and obesity)." (PMID 27654253, 2016). "Currently, DPP4 inhibitors are being used to treat diabetes mellitus and it is a useful therapeutic approach." (PMID 26975422, 2016). "Dipeptidyl peptidase 4 inhibitors (DPP4 inhibitors) have been used for severalyears in the management of type 2 diabetes mellitus." (PMID 26726045, 2016). "DPP-4 is abundant in the brush borders of kidney proximal tubule cells and is activated further in animal models of diabetes." (PMID 26959365, 2016). "Dipeptidyl peptidase-4 inhibitors are a class of oral hypoglycemic drugs and are used widely to treat type 2 diabetes mellitus in many countries." (PMID 27520566, 2016). "The expression of DPP-4 is substantially dysregulated in a variety of disease states, including inflammation, cancer, obesity, and diabetes." (PMID 27652270, 2016). "Because GIP and GLP-1 are rapidly inactivated by DPP4, DPP4 inhibitors are widely used for clinical treatment of diabetes as an insulin secretagogue." (PMID 27053237, 2016). "Experimental and clinical studies revealed that inflammatory states including diabetes mellitus (DM), obesity, and atherosclerosis show increased plasma DPP4 levels." (PMID 27654253, 2016). "Recent novel therapies for diabetes using incretin or DPP-4 inhibitors elicit biological vasoprotective effects that surpass glycemic control." (PMID 26881236, 2016). "Dipeptidyl peptidase-4 inhibitors (DPP4i) have been used for the treatment of type 2 diabetes mellitus (T2DM) as reversible inhibitors through interacting with DPP4 substrate and increase serum incretins such as glucagon-like peptide-1 (GLP-1)." (PMID 27881129, 2016). "We previously reported a patient with glucocorticoid-induced diabetes whose glucose levels were ameliorated by the use of DPP-4 inhibitor, sitagliptin." (PMID 25883713, 2015). "Dipeptidyl peptidase-4 (DPP-4) inhibitors are used for the treatment of the Type 2 diabetes mellitus (T2DM)." (PMID 26609328, 2015). "Patients in the DPP-4 inhibitor group demonstrated a longer duration of diabetes, a higher Charlson comorbidity score, and a larger number of hypoglycemic agents used compared with both the sulfonylurea and pioglitazone groups." (PMID 25992614, 2015). "Since DPP-4 inhibitors are dependent on the endogenous secretion of incretins, that class of drugs will theoretically be useful in early stages of diabetes, when the patient still retains a β cell population capable of responding to GLP-1 stimulation." (PMID 26075286, 2015). "While several changes in diabetes medication usage occurred, DPP4-inhibitor was the only oral diabetic agent that increased in frequency (+60%)." (PMID 25946187, 2015). "One of the most interesting and innovative aspects of incretin-based therapies, including DPP-4 inhibitors, is the putative cytoprotective effect on extrapancreatic organ or tissues target by diabetes, such as the heart, vessels, kidney, and retina." (PMID 26075286, 2015). "Only one patient was noted to be on a newer diabetes medication, DPP-4 inhibitor, which has only recently become widely available in Australia." (PMID 26074965, 2015). "Inhibitors of DPP4 have been then developed and are widely used as effective agents for the treatment of type 2 diabetes mellitus (DMT2; Pratley and Salsali, 2007)." (PMID 26136686, 2015).
diabetes (continued). "The most commonly used glucose lowering drugs in patients with previously known diabetes were metformin (57 %), insulin (27 %), sulfonylurea (25 %) and DPP-4 inhibitor (7 %)." (PMID 26427624, 2015). "Identifying the functionally relevant renal substrates of DPP4 will help us understand and anticipate long-term effects of DPP4 inhibition on the kidney in patients with diabetes." (PMID 26379674, 2015). "Dipeptidyl peptidase 4 inhibitors (DPP4inh) are novel oral diabetic agents used to lower blood glucose in patients with type 2 diabetes mellitus." (PMID 26379674, 2015). "Interest in this regard has been raised due to the frequently observed cutaneous complications occurring during diabetes and the ensuing potential of DPP4 inhibitors to control them." (PMID 26136686, 2015). "At present, GLP-1 analogs and DPP-4 inhibitors have been widely used in type-2 diabetes mellitus (T2DM) treatment." (PMID 26343632, 2015). "In a recent work, our group has also reported that sitagliptin prevented the diabetes-induced increase in DPP-4/CD26 activity and levels in serum and retina of streptozotocin- (STZ-) induced T1DM rats." (PMID 26075286, 2015). "Review of medication revealed a DPP-4 inhibitor, saxagliptin, which was started 3.5 months before this clinical followup for the management of type 2 diabetes mellitus." (PMID 26290759, 2015). "Dipeptidyl-peptidase-4 inhibitors (DPP4Is) are drugs for the treatment of type 2 diabetes mellitus (T2DM)." (PMID 26468883, 2015). "Although adenovirus delivery of human DPP4 into mouse has been developed to study MERS-CoV infection, in vivo rodent models for the investigation of DPP4-ADA interaction of relevance to human diabetes are currently unavailable." (PMID 26075284, 2015). "Of 15,892 T2DM patients (age, 74.2 ± 6.3 years; diabetes duration, 12.8 ± 8.9 years; HbA1c, 7.0±1.0%), dipeptidyl peptidase-4 inhibitor (DPP-4i) was the most prescribed medication among all oral hypoglycemic agents (OHAs)." (PMID 26566411, 2015). "Dipeptidyl-peptidase-4 inhibitors (DPP4Is) (sitagliptin, saxagliptin, vildagliptin, linagliptin and alogliptin) are a new class of drugs for the treatment of type 2 diabetes mellitus (T2DM)." (PMID 26468883, 2015). "Collectively, our present findings showing only slight improvement of glucose tolerance with sufficient DPP-4 inhibition can be explained by the use of older db/db mice with severe insulin resistance and diabetes." (PMID 25986579, 2015). "Expression of DPP4 is substantially dysregulated in a variety of disease states including inflammation, cancer, obesity, and diabetes." (PMID 26284071, 2015). "In this sense, DPP-4 inhibitors will theoretically be useful in early stages of diabetes, when the patient still retains a β cell population capable of responding to GLP-1 stimulation." (PMID 26075286, 2015). "As DPP4 is present on the brush border (apical side) of kidney proximal tubular cells, DPP4 inhibition is likely to alter the degradation/regulation of peptides in the lumen and thus influence the tubular cell structure or function in diabetes." (PMID 26379674, 2015). "A small number of trials have investigated the clinical use of DPP4 inhibitors in the treatment of conditions other than diabetes." (PMID 26021829, 2015). "Dipeptidyl peptidase-4 (DPP4) inhibitors are currently used in the treatment of type 2 diabetes mellitus to improve glucose tolerance by increasing the half-lives of glucagon-like peptide-1 (GLP-1) and glucose-dependent insulinotropic peptide." (PMID 26021829, 2015). "The importance of DPP4 for the scientific and medical community raised substantially since the approval of DPP4 inhibitors for the treatment of type 2 diabetes mellitus (T2DM)." (PMID 26284071, 2015). "Vildagliptin, a dipeptidyl peptidase-4 (DPP-4) inhibitor, is wildly used to treat type 2 diabetes mellitus (T2DM) with mono- or combination-therapy." (PMID 27382546, 2015).